CHGB (chromogranin B)
Diseases named in the same sentence as CHGB in open-access papers (continued):
Sharing a sentence is not in itself a finding about the gene and the disease.
tumor (24 papers, 2007 to 2025). "In addition, PRL-PA-specific upregulation of genes caused by copy number amplification includes chromogranin B (CHGB), which has been linked to tumor progression in PRL-PAs, further supporting the role of genomic copy number variation in PA progression." (PMID 33472173, 2020). "Abnormal expression of CHGB gene has been reported in many tumor types, and its upregulated expression is highly correlated with metastasis." (PMID 35935970, 2022). "Compared to control subjects, chromogranin A level was higher in the CgA+ group (p = 0.0086), thrombopoietin (p = 0.0040) and chromogranin B (p = 0.0070) in the CgA− group, while interleukin-6 was high in both tumor groups (p ≤ 0.0090)." (PMID 33383764, 2020). "It has a sensitivity higher than 90% in many studies (86% for chromogranin-B and 5% for chromogranin-C) and is well correlated to tumor burden, especially in the presence of liver metastasis, making it a valuable marker in followup after treatment is initiated." (PMID 23316222, 2012). "The profiled tumor cells expressed most general PNEC markers (e.g. SCG5, CHGB, SCG2, PCSK1N, CHGA, SCG3) indicating retention of PNEC identity." (PMID 36469459, 2022). "Tumor cell cluster 6 expressed neuroendocrine markers (e.g., CHGA and CHGB)." (PMID 36008377, 2022). "As expected, NB5t primary cells showed increased expression of mesenchymal genes (NT5E, ENG, ACTA2, MME, CD44, VIM or ALPL), while NB5t tumor sample expressed mostly neuronal genes (TH, ENO2, NCAM1, DDC or CHGB) reflecting the neuroblastic phenotype of stage 4/M NB tumors." (PMID 29163787, 2017). "Hence, we aimed to retrospectively collect pathologically identified PPGL tumor tissues from our center and investigate the expression of apelin and SUCLG2 along with previously studied ERBB-2, CNTN4, CHGB, and SDHB in metastatic and non-metastatic PPGLs." (PMID 35574028, 2022).
cancer (11 papers, 2015 to 2026). A tumor composed of atypical neoplastic, often pleomorphic cells that invade other tissues. "While CHGB genetic variants have been associated with cardiovascular disease risk and the protein regulates ion channels to maintain secretory granule homeostasis, its role in cancer remains poorly understood and warrants further investigation." (PMID 40575157, 2025). "For instance, the top-ranked common gene, C-X-C motif chemokine ligand 10 (CXCL10) is overexpressed in 30 cancer types, whereas chromogranin B (CHGB) expression is downregulated in 16 of the 31 TCGA solid cancers." (PMID 41567365, 2026). "TWF2 mainly participates in cancer cell proliferation signalling pathways through interaction with chromogranin B (CHGB)." (PMID 26515236, 2015). "Surprisingly, we found that many cancer cells from P11 not only coexpressed NKX2-1 and TP63 but also showed high expression of CHGB and UCHL1, which are markers of neuroendocrine cells." (PMID 35962452, 2022). "We found that the cancer subtype markers (GRP, CHGB, NEUROD1, and CHGA for NET; KRT5, DSC3, KRT6B, TP63, and KRT6A for SCC; and NKX2-1, KRT7, NAPSA, and MUC1 for ADC) were specifically expressed in the corresponding cancer subtypes." (PMID 35962452, 2022).
infection (2 papers, 2010 to 2022). The state of being infected such as from the introduction of a foreign agent such as serum, vaccine, antigenic substance or organism. "Moreover, the abundance of the panendocrine cell markers chromogranin A (CHGA) and CHGB, which are weakly upregulated during the early stages of infection, was decreased from 17 to 48 DPI, and ChgB was significantly transcriptionally downregulated from 13 to 48 DPI compared to UI mice." (PMID 35100877, 2022).
adenocarcinoma (1 paper, 2020). A common cancer characterized by the presence of malignant glandular cells. "In addition, epithelial cells of patient #6 consisted of a group of NE cells (cluster 4, expressing ASCL1, CHGA, and CHGB), a group of basal cells (cluster 8, expressing KRT5, KRT14, and KRT15) as well as the remaining ARhigh luminal cells, presenting mixed features of both adenocarcinoma and NEPC." (PMID 33328604, 2020).
CHGB also shares sentences with these, for which no sentence is quoted: heart failure (3 papers); dementia (2); multiple sclerosis (2); neurodegenerative disease (2); paraganglioma (2); cardiovascular disease (1); colorectal cancer (1); head and neck squamous cell carcinoma (1); head and neck tumors (1); invasive ductal carcinoma of the breast (1); medullary thyroid carcinoma (1); migraine (1); nasopharyngeal carcinoma (1); periodontitis (1); primary immunodeficiency (1); type 1 diabetes (1); type 2 diabetes (1); Vestibular schwannoma (1).